EIF6 (eukaryotic translation initiation factor 6)
Diseases named in the same sentence as EIF6 in open-access papers (continued):
Sharing a sentence is not in itself a finding about the gene and the disease.
glioma (3 papers, 2019 to 2022). A benign or malignant brain and spinal cord tumor that arises from glial cells (astrocytes, oligodendrocytes, ependymal cells). "eIF5 expression showed a high variability throughout all samples and eIF6 (IV: p < 0.01) expression was only elevated in high grade gliomas (HGGs) compared to CCBT." (PMID 33807050, 2021). "Supporting a role for eIF6 in gliomas, we found that EIF6 is overexpressed in gliomas including in GBM for all subtypes except the proneural." (PMID 31795417, 2019). "EFTUD1 being overexpressed in gliomas might alter eIF6 subcellular localization and consequently prevent eIF6 from performing its functions." (PMID 31795417, 2019). "Similarly, circ-EIF6 could encode EIF6-224 aa, and circ-FBXW7 could encode FBXW7-185aa, to regulate TNBC progression and glioma tumorigenesis, respectively." (PMID 36139074, 2022). "Protein and mRNA expressions of eIF3B, eIF3I, eIF4A1, eIF4H, eIF5 and eIF6 were significantly increased in high grade gliomas compared to CCBT and partially in low grade gliomas." (PMID 33807050, 2021).
melanoma (3 papers, 2015 to 2023). A malignant, usually aggressive tumor composed of atypical, neoplastic melanocytes. "We conclude that the IFs keratins are the downstream effectors of IF6, and the up-regulation of eIF6 causes a poor melanoma survival rate of patients by de-methylating and activating of keratin genes." (PMID 35707354, 2022). "Our results revealed that eIF6 was highly over-expressed in melanomas compared to normal skin specimens, and thus the abnormally high level of eIF6 can be a diagnostic marker for melanoma." (PMID 35707354, 2022). "In summary, the up-regulated eIF6 could be a potential diagnostic and prognostic biomarker indicating poor survival of melanoma." (PMID 35707354, 2022). "The up-regulated eIF6 could be a potential diagnostic and prognostic biomarker of melanoma." (PMID 35707354, 2022). "Thus, eIF6 is a promising diagnostic and prognostic candidate in melanoma." (PMID 35707354, 2022). "In this work, we investigated the eIF6 expression features and its role in melanoma progression using clinical specimens and the TCGA database." (PMID 35707354, 2022). "This study offered a better understanding of the functional role of eIF6 in cancer progression and provided new insights into the potential role of eIF6 as a melanoma predictive biomarker." (PMID 35707354, 2022). "Herein we proposed that eIF6 is a promising biomarker to improve the assessment of clinical melanoma since the early clinical manifestations of melanoma often look like nevi." (PMID 35707354, 2022). "In this study, the skin melanoma samples exhibited significantly increased eIF6 expression levels than the normal skin samples, corresponding to the up-regulated melanoma cells division rates." (PMID 35707354, 2022). "It is possible that eIF6 acts as a rate-limiting factor that induces higher dynamic cell skeleton gene expression and promotes the proliferation and migration of melanoma, which relates to a poorer prognosis." (PMID 35707354, 2022). "In contrast, previous research found over-expression of eIF6 in ovarian cells and melanoma cell lines can effectively increase cell mobility and proliferation via CDC42 up-regulation." (PMID 35707354, 2022). "The results indicated that melanoma cells had higher levels of eIF6 expression when compared to adjacent normal tissues." (PMID 35707354, 2022). "The in vitro experiments proved that eIF6 over-expressed A375 melanoma cells had a faster proliferation and migration rate." (PMID 35707354, 2022). "In melanoma, there were 10305 genes had higher methylation levels in the eIF6-low group, while 5395 genes in the eIF6-high group had higher methylation tendencies." (PMID 35707354, 2022). "Our study showed that the eIF6 up-regulation also occurs during melanoma tumorigenesis, which relates to a poorer prognosis." (PMID 35707354, 2022). "We examined the prognostic value of eIF6 according to its expression and analyzed the patients’ survival data to infer its potential melanoma-promoting mechanisms." (PMID 35707354, 2022). "The eIF6 expression through all the stages of melanoma development was further investigated by GEPIA analysis, the results showed that compared with the stage 0, eIF6 level was up-regulated from stage I to stage IV." (PMID 35707354, 2022). "We compared the survival curves of melanoma patients with high or low eIF6 expression levels and grouped them according to gradient inclusion criteria." (PMID 35707354, 2022). "The cellular function of eIF6 was investigated using the melanoma cell line A375." (PMID 35707354, 2022). "The increased expression of eIF6 in melanoma could be attributed to increased transcription factor binding caused by tumorigenesis." (PMID 35707354, 2022). "In vitro, over-expression of eIF6 increased the proliferation and migration of melanoma cells." (PMID 35707354, 2022). "Additionally, the up-regulated eIF6 expression was further confirmed by Timer analysis, which suggest the potential effectiveness of eIF6 in early stage melanoma diagnosis." (PMID 35707354, 2022).
melanoma (continued). "Immunochemistry was used to determine the level of eIF6 protein in the melanoma specimens." (PMID 35707354, 2022). "In all of the survival curves, melanoma patients with high eIF6 expression had worse prognoses." (PMID 35707354, 2022). "In addition, KRT17 and KRT15 were up-regulated and demethylated in the eIF6-high expressed melanoma, suggesting that DNA demethylation was a potential transcription regulation mechanism of eIF6." (PMID 35707354, 2022). "It reached 25% at 48-hours, indicating over-expression of eIF6 could accelerate the migration of malignant melanoma cells in vitro." (PMID 35707354, 2022). "Finally, over-expression of eIF6 in primary melanoma cell lines (WM793) induced cdc42 up-regulation and increased motility and invasiveness, thus demonstrating that the tumor-promoting ability of this initiation factor is not restricted to the A2780 cell line." (PMID 25886394, 2015). "Therefore, the abnormal up-regulation of eIF6 in melanoma is a sign of cancer cell proliferation." (PMID 35707354, 2022). "Additionally, the eIF6 level is also predictive of melanoma prognosis." (PMID 35707354, 2022). "Finally, we explored the effects of eIF6 over-expression on WM793 primary melanoma cell lines." (PMID 25886394, 2015). "Among these five types of cancers, the eIF6’s impact on LGG, LIHC and LUAD progression had been reported previously, while that on melanoma was still unclear." (PMID 35707354, 2022). "In our study, all over-expressed keratin proteins, in accordance with over-expressed eIF6, had a negative correlation with melanoma prognosis." (PMID 35707354, 2022). "To test whether the results of eIF6 over-expression on the migratory activity of the cells were generalizable to other cell line models, we extended our analysis on WM793 primary melanoma cell lines." (PMID 25886394, 2015).
ovarian serous adenocarcinoma (3 papers, 2008 to 2019). An adenocarcinoma that arises from the ovary and is characterized by the presence of malignant epithelial cells that, in well differentiated tumors, resemble the epithelium of the fallopian tube or, in poorly differentiated tumors, show anaplastic features and marked nuclear atypia. "Patients with ovarian serous adenocarcinomas showed eIF6 overexpression and a correlation with patients’ overall survival." (PMID 31586263, 2019). "Notably, over-expression of eIF6 has been observed in a significant proportion of ovarian serous adenocarcinomas and hematological cancers." (PMID 22348144, 2012). "This increase in cytoplasmic eIF6 levels in human FFPE tissue specimens was already reported in CRC, ovarian serous adenocarcinoma, and pleural mesothelioma." (PMID 31586263, 2019).
pleural mesothelioma (3 papers, 2015 to 2022). A neoplasm that arises from the mesothelial cells of the pleura. "Interestingly, inhibition of eIF6 could reduce cell growth by impairing lactate and ATP production in Malignant Pleural Mesothelioma." (PMID 35794622, 2022).
thyroid carcinoma (3 papers, 2018 to 2022). "In thyroid carcinoma, eIF6 promotes tumor growth by regulating MIR-144-3p/TGF-α, and the knockout of eIF6 enhances cisplatin sensitivity." (PMID 34922580, 2021).
colon carcinoma (2 papers, 2021 to 2023). "Expression of the eIF6-N106S mutant markedly sensitized colonic cancer cells and inhibited cell proliferation similar to the eIF6-Y151A mutant." (PMID 36651285, 2023). "In addition, our 2D-gel analysis of endogenous eIF6 in colon carcinoma cells indicates extensive phospho-modification." (PMID 36651285, 2023).
diabetes (2 papers, 2015 to 2017). "In mice, Eif6 expression was significantly upregulated in response to a combination of a high-fat diet and metformin, a drug commonly used to treat diabetes." (PMID 29117557, 2017). "The capability of translation, and eIF6, to steer metabolism has wide implications in diabetes." (PMID 26383020, 2015).
esophageal cancer (2 papers, 2022 to 2025). A primary or metastatic malignant neoplasm involving the esophagus. "Although eukaryotic initiation factor 6 (eIF6) is a novel therapeutic target, data on its importance in the development of esophageal carcinoma (ESCA) remains limited." (PMID 35794622, 2022).
Hepatic steatosis (2 papers, 2021 to 2023). Steatosis is a term used to denote lipid accumulation within hepatocytes. "Collectively, our results demonstrate that 50% eIF6 reduction slows down hepatic steatosis and fibrosis." (PMID 34385447, 2021).
Insulin resistance (2 papers, 2015 to 2021). Increased resistance towards insulin, that is, diminished effectiveness of insulin in reducing blood glucose levels. "We analysed whether a relationship between eIF6 levels and insulin resistance, could be found in humans." (PMID 26383020, 2015).
liver cancer (2 papers, 2021 to 2025). An epithelial or non-epithelial malignant neoplasm that arises from the liver. "To directly test the relationship between eIF6 protein expression and the greater risk of progression to HCC, we addressed, in vivo, the effect of eIF6 depletion on liver cancer development." (PMID 34385447, 2021). "Notable examples include circ-EIF6, encoding the peptide EIF6-224aa31 through IRES-driven translation, which interacts with MYH9 to activate the Wnt/β-catenin pathway, and circZKSCAN1, which enhances sorafenib sensitivity in liver cancer." (PMID 40713830, 2025). "Furthermore, YY1 mRNA levels and its upregulated targets in conditions of eIF6 depletion individually showed a consistent trend with benign prognosis in primary liver cancer." (PMID 34385447, 2021).
liver disease (2 papers, 2021 to 2022). "Together, these findings show that there is a positive correlation between eIF6 expression, lipid accumulation, and the progression of liver disease." (PMID 34385447, 2021). "Here, we unveil the existence of an evolutionarily conserved translation circuit optimized for lipid accumulation and predisposing to tumor progression and provide proof-of-concept that the manipulation of eIF6 can be exploited for preventing liver disease progression." (PMID 34385447, 2021).
lymph node metastasis (2 papers, 2021 to 2022). "Moreover, cytoplasmic eIF6 was significantly correlated with the tumor size, lymph node metastasis and clinical stage of patients." (PMID 34922580, 2021). "Subsequent analyses revealed that there was significant correlation between the eIF6 expression and SUVmax (p = 0.010) or SUVmean (p = 0.018), but not with gender, age, differential status, lymph node metastasis, p stage, TLG or MTV." (PMID 35794622, 2022).
malignant mesothelioma (2 papers, 2015 to 2021). A malignant neoplasm of the pleura or peritoneum, arising from mesothelial cells. "We propose that eIF6 is necessary for malignant mesothelioma growth, in vivo, and can be targeted by kinase inhibitors." (PMID 26462016, 2015). "We show that eIF6 is highly expressed and activated in malignant mesotheliomas, and that inhibition of either its activity or phosphorylation reduces tumor burden and tumor growth." (PMID 26462016, 2015). "We will discuss our findings according three lines, the relevance for malignant mesothelioma, the feasibility and significance to target eIF6, and the molecular mechanism which may account for the increased eIF6 expression in mesothelioma." (PMID 26462016, 2015). "In conclusion, we suggest that modulation of eIF6 levels and activity may lead to a therapeutical avenue in tumor therapy, especially where eIF4E inhibition by rapalogs is not effective, as in malignant mesothelioma." (PMID 26462016, 2015).
mesothelioma (2 papers, 2015 to 2024). A usually malignant and aggressive neoplasm of the mesothelium which is often associated with exposure to asbestos. "In previous studies, we demonstrated that translational control of gene expression plays a crucial role in mesothelioma progression, either directly through eIF6 or indirectly through microRNA association with polysomes." (PMID 38397189, 2024). "We found that eIF6 is overexpressed and hyperactivated in mesotheliomas and that inhibition of its expression or phosphorylation delays tumor progression." (PMID 26462016, 2015). "Molecular analysis reveals that eIF6 manipulation affects the metabolic status of malignant mesothelioma cells." (PMID 26462016, 2015). "In conclusion, analysis of three separate mesothelioma datasets showed that the combination of eIF6 expression and phosphorylation correlates with negative survival, raising the question whether its inhibition may be beneficial." (PMID 26462016, 2015).
myeloid malignancies (2 papers, 2022 to 2025). "Somatic mutations in EIF6 or its haploinsufficiency due to loss of 20q have been found in two-thirds of patients with SDS who have a decreased risk of developing myeloid malignancies." (PMID 39964763, 2025). "Deletions of the EIF6 locus in other forms of myeloid malignancies might therefore be functionally irrelevant and merely coincidental." (PMID 35812385, 2022).
neutropenia (2 papers, 2021 to 2025). A decrease in the number of neutrophils found in the blood. "Using this criterion, we did not detect EIF6 mutations in the 15 healthy controls, the 5 SDS patients post-HSCT, the 5 patients with neutropenia of unknown molecular origin, or the SRP54-deficient patient." (PMID 34413298, 2021).
ovarian tumour (2 papers, 2008 to 2022). "We did not confirm data from previous groups showing that eIF6 underexpression in ovarian tumour tissue to worse RFS and OS." (PMID 35718769, 2022). "We examined the relative expression levels of eIF6 and Dicer on TMAs including 56 primary OSC and 15 recurrent ovarian tumours and determined whether any correlation exists between the two." (PMID 18442408, 2008).
steatosis (2 papers, 2021 to 2022). Increased lipid within the cytoplasm of cells. "This prompted us to test whether the pharmacological targeting of eIF6 reduces lipogenesis and lipid accumulation in an in vitro model of steatosis and C/EBPβ polysomal association." (PMID 34385447, 2021). "At the early time point, eIF6 het mice had less fibrosis, as shown by Sirius Red staining, as well as less steatosis and reduced eIF6 levels." (PMID 35887068, 2022). "Morphological observation of eIF6 heterozygous liver sections showed that they had smaller neoplastic regions surrounded by extensive areas of steatosis compared to wt ones." (PMID 34385447, 2021). "Histological examination of liver sections showed that eIF6+/− mice displayed less steatosis and less Oil Red O accumulation." (PMID 34385447, 2021).
acute myeloid leukemia (1 paper, 2021). Acute myeloid leukemia (AML) is a group of neoplasms arising from precursor cells committed to the myeloid cell-line differentiation. "Longitudinal analysis will be necessary to determine whether clonal expansion promoted by the acquisition of somatic EIF6 mutations delays or abrogates the emergence of hematological complications such as aplastic anemia, myelodysplastic syndrome (MDS), or acute myeloid leukemia (AML)." (PMID 34413298, 2021).
adenoma (1 paper, 2020). A neoplasm arising from the epithelium. "Data in the Human Protein Atlas25 indicated that the expression of EIF6, as measured by IHC, is already high in normal colon tissue, leaving little room to detect increased EIF6 protein expression in adenomas and CRCs." (PMID 31411736, 2020). "POFUT1, RPRD1B and EIF6 were identified as putative drivers of adenoma‐to‐carcinoma progression." (PMID 31411736, 2020).
Alzheimer disease (1 paper, 2017). A progressive, neurodegenerative disease characterized by loss of function and death of nerve cells in several areas of the brain leading to loss of cognitive function such as memory and language. "This included diseases such as Alzheimer’s disease, which exhibited a significant decrease in Eif6 expression in neuronal cells." (PMID 29117557, 2017).
astrocytomas (1 paper, 2021). "eIF5 (p < 0.05) and eIF6 (p < 0.001) protein levels also varied within astrocytoma sample and significantly increased protein levels were only detected in GBM patients compared to CCBT." (PMID 33807050, 2021). "We showed that the expression of eIF3B, eIF3I, eIF4A1, eIF4H and eIF6 was significantly increased in astrocytomas, in particular in GBM, for protein and mRNA levels." (PMID 33807050, 2021). "Besides the already known eIFs, we demonstrated significantly elevated protein levels of eIF3D, eIF3H, eIF3I, eIF3M, p-eIF4G, eIF4H, eIF5 and eIF6 in astrocytoma tissue compared to CCBT." (PMID 33807050, 2021).
atherosclerosis (1 paper, 2024). A disease characterized by the build-up of fatty material and calcium deposition in the arterial wall resulting in partial or complete occlusion of the arterial lumen. "According to these data, we found that eIF6 deficiency alleviates atherosclerosis and improves a stable plaque phenotype." (PMID 39225466, 2024). "ApoE−/− and ApoE−/−/eIF6+/− mice on normal chow diet or a high-fat diet were treated for 16 weeks; eIF6 deficiency was evaluated atherosclerosis." (PMID 39225466, 2024). "eIF6 deficiency protected against atherosclerosis by regulating the composition of gut microbiota and metabolites." (PMID 39225466, 2024). "In conclusion, our study demonstrated that eIF6 deficiency regulates the gut microbiota and a wide range of metabolites in atherosclerosis ApoE−/− mice." (PMID 39225466, 2024). "Therefore, eIF6 deficiency reduced lipid absorption and protected from high-fat diet-induced atherosclerosis." (PMID 39225466, 2024). "We want to validate whether eIF6 deficiency can alleviate atherosclerosis." (PMID 39225466, 2024). "To explore the role of eIF6 in regulating gut microbiota on atherosclerosis, we constructed a double knockout mouse model, ApoE−/−/eIF6+/− mice." (PMID 39225466, 2024). "In the study, we explore the relationship of eIF6 and gut microbiota with atherosclerosis." (PMID 39225466, 2024). "We found that eIF6 regulated the fatty acid synthase to inhibit the atherosclerosis." (PMID 39225466, 2024). "In order to investigate the potential role of the gut microbiota in mediating the beneficial effects of eIF6 on alleviating atherosclerosis development, we performed 16S rDNA gene sequencing on fecal samples of mice that were administered a standard NCD or HFD treatment." (PMID 39225466, 2024). "However, the role of eIF6 in the regulation of the gut microbiota in atherosclerosis has not yet been fully confirmed." (PMID 39225466, 2024).